TFDP1 (transcription factor Dp-1)
Diseases named in the same sentence as TFDP1 in open-access papers (continued):
Sharing a sentence is not in itself a finding about the gene and the disease.
non-small cell lung carcinoma (1 paper, 2021). A group of at least three distinct histological types of lung cancer, including non-small cell squamous cell carcinoma, adenocarcinoma, and large cell carcinoma. "The mRNA expression levels of COMMD3, COMMD4, COMMD5, COMMD6, and COMMD8 were also significantly downregulated in non-small cell lung cancer (NSCLC) cell lines, whereas COMMD9 was up-regulated and promotes the development of NSCLC by interacting with the TFDP1/E2F1 through the COMM domain." (PMID 33768002, 2021).
papillary thyroid carcinomas (1 paper, 2021). "The transcription factor TFDP1 is a gene with significant somatic copy number alterations and corresponding somatic gene expression changes were observed in papillary thyroid carcinomas, even though whose functions remain uncovered in cancer." (PMID 34316711, 2021).
prostate adenocarcinoma (1 paper, 2022). "However, there was a weak negative correlation for TNRC6C in TGCT; TFDP1 in LAML; CDKN2C in prostate adenocarcinoma (PRAD); and CDKN2A in KIRC and THCA." (PMID 35911954, 2022).
prostate tumors (1 paper, 2025). "Both OTX2 and SREBP2 have been implicated in lineage plasticity of prostate tumors and are known regulators of C-MYC34–36, while TFDP1 promotes the proliferation and is frequently upregulated advanced disease." (PMID 40770488, 2025).
psoriasis (1 paper, 2013). An autoimmune condition characterized by red, well-delineated plaques with silvery scales that are usually on the extensor surfaces and scalp. "Many DEG-coded proteins (CCNA2, FYN, PIK3R1, CTGF, F3) and transcription factors (AR, TFDP1, MEF2A, MECOM) were identified as central nodes, suggesting their potential role in psoriasis pathogenesis." (PMID 24303025, 2013). "CCNA2, TFDP1 and MECOM might play role in the hyperproliferation of keratinocytes, whereas FYN may be involved in the disturbed immunity in psoriasis." (PMID 24303025, 2013).
squamous cell carcinoma (1 paper, 2013). A carcinoma arising from squamous epithelial cells. "Frozen NSCLC tissue-based microarray analysis revealed that E2F6, TFDP1, SUV39H1, and HMGA1 are significantly upregulated in both the adenocarcinoma and squamous cell carcinoma samples." (PMID 24564251, 2013). "We found that E2F6, HMGA1, IRF1, and TFDP1 were upregulated and RBL1, SUV39H1, and HNRPD were downregulated or aberrantly expressed in adenocarcinoma and squamous cell carcinoma, which are the sub-types of NSCLC." (PMID 24564251, 2013). "Therefore, combining the microarray and qPCR results, upregulation of E2F6, HMGA1, IRF1, and TFDP1 and downregulation or no expression of SUV39H1, RBL1, HNRPD can be used as diagnostic markers of NSCLC, and, in particular, adenocarcinoma and squamous cell carcinoma." (PMID 24564251, 2013).
cancer (30 papers, 2010 to 2025). A tumor composed of atypical neoplastic, often pleomorphic cells that invade other tissues. "TFDP1, mutated only in the intra-pelvic recurrences regions, participates in cell cycle control modulating E2F pathway, and mutations in this gene can be found in various cancer databases." (PMID 26620706, 2015). "A comparison of gene expression profiles of FACS-sorted double positive keratinocytes isolated from UV-treated WT and TG mice indicated increased expression of Pes1, Rad21, Tfdp1, and Cks1b genes in TG mice linked to cell transformation, invasion, and metastasis of cancer cells." (PMID 23738074, 2013). "Therefore, therapeutic strategies aimed at restoring miR-1-3p expression and reducing TFDP1 activity may provide a synergistic effect to inhibit HBV-associated cancer development." (PMID 41425093, 2025). "recently showed that cell cycle signaling was associated with high cancer stemness of EAC, such as E2F3, CHEK1, CDC20, SMC3, and TFDP1." (PMID 35785171, 2022). "Several genes located in 13q34 have been associated with a worse prognosis in other cancers, including CUL4A and TFDP1, IRS2 and CDC16." (PMID 35887382, 2022). "Of the top 207 transcripts annotated as ‘cell cycle’ by GO analysis, we focused on nine well-known cell cycle regulators (CCNA2, CCND1, CDK6, CHK1, CHK2, MAPK1, MAP2K1,SKP2, and TFDP1) for further analyses, due to their known functions in cancers." (PMID 26958940, 2016). "The miR-1-3p has been widely reported to act as a tumor suppressor by downregulating multiple oncogenes across different cancer types, whereas TFDP1 functions as a transcriptional co-factor that promotes oncogene expression and tumor progression in several malignancies." (PMID 41425093, 2025). "And in 23 other cancer types, TFDP1 remains the significance in 21 types of cancer." (PMID 30697230, 2018). "Cancers displaying unfavorable risk with high ALT (BRCA, SARC, and LUAD) may be regulated by the transcriptional factors E2F4, TFDP1, E2F1, E2F7, and SIN3A (FDR = 0.001) in the DNA repair pathway, including genes repairing DNA damage such as CENPI, CLSPN, TOPBP1, and MCM4." (PMID 32784588, 2020). "Thus, mutant TFDP1 could facilitate E2F release and promote cell cycle progression in the development of cancers." (PMID 31925297, 2020). "Hence, TFDP1 may play an important role on the transcriptional regulatory network of PIP4K2A to impact on the survival rate in multiple cancer types." (PMID 30697230, 2018). "However, the TF-mRNA-miRNA network analysis with the hub genes and the recent trend of targeting TF in cancer therapy highlight the importance of identifying common transcriptional and post-transcriptional regulators for the hub genes, such as TFDP1 and miR-1-3p." (PMID 41425093, 2025). "Some of these genes (e.g. CENPF, MLKL, TFDP1, MCF2L) have a known influence on cancer, while others (e.g. NUP54, BBS1 and HTT) have been superficially studied under the tumoral context." (PMID 34316711, 2021). "We finally obtained eight bona fide cancer driver genes, including CEP57, HNRNPL, KLF5, OXA1L, PAFAH1B1, RBM39, SYT13, and TFDP1." (PMID 31925297, 2020). "The downregulated genes belonged mainly to the “cancer” biofunction (RPS27A, HNRNPA1, STIP1, and TFDP1)." (PMID 22619672, 2012). "Our analysis identified E2F4 and TFDP1, two core components of the DREAM transcriptional repression complex, as transcriptional modulators preferentially activated by irinotecan in EPCAM+/CD44+/CD166+ as compared to EPCAM+/CD44neg/CD166neg cancer cells." (PMID 39896677, 2025). "In summary, we identified a group of malignant epithelial cells that may be regulated by TFDP1 during HNSCC progression and promote cancer development." (PMID 38519500, 2024). "Similarly, markers of E2F-dependent transcription are mostly represented overall cancers types, as well as E2F4 and TFDP1, which regulate genes involved in key processes of malignant transformation, such as cell cycle regulation and DNA replication." (PMID 32015379, 2020).
cancer (continued). "Among the most representative candidate cancer driver genes are HNRNPL, KLF5, and TFDP1." (PMID 31925297, 2020). "Strikingly, TFDP1 exhibits the strongest consistency with PIP4K2A in the same direction in five out of six cancer types (i.e., KIRC, LAML, SARC, BLCA, and LIHC) but not STAD." (PMID 30697230, 2018). "In addition, we noticed seven of them have been included in the latest version of The Network of Cancer Genes35 (KLF5, OXA1L, RBM39, and TFDP1) or CancerMine36 (HNRNPL, KLF5, PAFAH1B1, SYT13, TFDP1), two manually curated cancer gene databases, further confirming our findings." (PMID 31925297, 2020). "In our results, calycosin affected two check points gene transcription; for example TFDP-1 and SKP2 were markedly downregulated and CDC2 and CCNB1 were upregulated expression and downregulated expression of CDKN2D which may block the G1/S and G2/M transition in cancer cells." (PMID 24455688, 2013). "Besides, MS13 treatment in DU 145 and PC-3 cells has shown the downregulation of PPP3CB, TFDP1, SMAD3, and ENDOG, which the anti-cancer activity have not been reported in PCa but noted in other cancers." (PMID 34366863, 2021).
tumor (29 papers, 2009 to 2025). "Elevated expression of TFDP1 was associated significantly with larger tumor size and down-regulation of TFDP1 inhibited the growth of Hep3B cells." (PMID 36967768, 2023). "Tfdp1 encodes a TF that binds to the promoter regions of a number of genes whose products are involved in cell cycle regulation or in tumor proliferation." (PMID 28725177, 2017). "Tumors overexpressing either CUL4A or TFDP1 were associated with tumor proliferation and cell cycle progression markers." (PMID 19995430, 2009). "Thus, TFDP1 is not only a strong candidate to drive Amp13q34, but also a gene involved in different components of tumorigenesis, causing higher tumor aggressiveness and a poor patient prognosis." (PMID 19995430, 2009). "TFDP1 also contributes to tumor development, where its abnormal activation often leads to sustained transcription of E2F target genes, thereby promoting G1–S phase transition and unlimited proliferation." (PMID 41184982, 2025). "In colon cancer, the direct binding of miR‐4711‐5p to TFDP1 can result in the arrest of tumor cells in the G1 phase." (PMID 41458288, 2025). "Downregulation was observed for the genes CCNG2 (−9.0-fold), CCND1 (−5.84-fold), TFDP1 (−5.84-fold), CDC34 (−5.14-fold), and HUS1 (−4.52-fold), which are normally linked to the development of various tumor types when overexpressed." (PMID 39337305, 2024). "When tumor cells were induced to overexpress TFDP1, their migration and invasion capacity were significantly increased, and vice versa." (PMID 38519500, 2024). "The most prominent finding was that TFDP1 was highly activated in cluster 1 and was the top-ranked TF regulon, which was consistent with the trend revealed by the heatmap and tumor samples in our validation cohort." (PMID 38519500, 2024). "Thus, we speculated that tumor progression caused by overexpression of CKAP2 is related to TFDP1." (PMID 39403723, 2024). "The correlations of PIP4K2A with TFDP1 tend to exhibit tumor-specific (i.e., significant in 21/23 tumors but 9/20 normal tissues), while that with MED16 is tend to be in control-specific manner (i.e., significant in 14/23 tumors but 15/20 normal tissues)." (PMID 30697230, 2018). "TFDP-1 is one of the driver genes, which leads to higher tumor aggressiveness through deregulation of cell-cycle." (PMID 24455688, 2013). "We propose that CUL4A and TFDP1 are likely the driver genes for this genomic amplification, leading higher tumor aggressiveness through deregulation of cell cycle." (PMID 19995430, 2009). "Several studies have reported that the expression of TFDP1 is related to tumor proliferation." (PMID 41458288, 2025). "Moreover, UGZ–1004 exposure led to the downregulation of genes associated with tumor development, including CCND1 and TFDP1, mitigating potential tumorigenic risks." (PMID 39337305, 2024). "Kohichiroh Yasui also found that since it promoted tumor cell growth, elevated TFDP1 expression may significantly affect HCC progression." (PMID 37787988, 2023). "Furthermore, TFE3, TFDP1, NFYB, and RB1, associated with the cell cycle and apoptosis, were inferred in FSTL1+ tumor cells." (PMID 37430270, 2023). "In conclusion, overexpression of TFDP1 may contribute to the progression of some HCCs by promoting the growth of the tumor cells." (PMID 36967768, 2023). "miR-4711-5p significantly inhibited tumor growth by downregulating TFDP1 mRNA and protein levels." (PMID 35685832, 2022). "In HCC, overexpression of TFDP1 may contribute to tumorigenesis by up-regulating expression of CCNE1 that encodes for cyclin E of the cell cycle G1/S transition, resulting in tumor progression." (PMID 26684807, 2015). "These associations support that the overexpression of CUL4A and TFDP1, even though it is correlated with Amp13q34, is not exclusive of basal-like tumors, but still relates to higher tumor aggressiveness." (PMID 19995430, 2009). "This suggests that TFDP1 overexpression may contribute to tumor cell progression and growth." (PMID 39337305, 2024).
tumor (continued). "In the same tumour sets, the expression levels of target molecules (KLF5, TFDP1 and MDM2) decreased at the mRNA and protein levels." (PMID 32066912, 2020). "Among 90 tumor regulated genes 95% had consensus binding sites for c-Myc (represented by PWM EBOX_Q6_01) while the combined EBOX_Q6_01 and TFDP1 (represented by PWM E2F_Q4_01) PWMs fitted 58 gene specific promoters or 65% of regulated genes." (PMID 27602772, 2016). "We identified some mutation markers specific to tumor types, including some typical tumor‐related genes (e.g., TP63, ABCC1, ABCC5, and TFDP1 in ESCA) as well as numerous noncoding genes (e.g., NPSR1‐AS1 and AC079466.1 in HCC) and pseudogenes (e.g., SDHAP3 and TPTEP1 in LUAD)." (PMID 38010945, 2024). "Kohichiroh Yasui also found that elevated TFDP1 expression may significantly affect HCC progression, as it promoted tumor cell growth." (PMID 33771191, 2021). "Downregulated TFDP-1, CDKN2D, and SPK2 and upregulated CDC2 and CCNB1 might affect cell cycle of tumor cells." (PMID 24455688, 2013). "This miRNA suppressed CSC properties, possessed various anti-tumour effects against CRC cell lines and CRC cell cultures derived from clinical CRC samples through direct inhibition of KLF5 and MDM2, and provoked G1 arrest via direct inhibition of TFDP1, which forms a heterodimer with E2F1." (PMID 32066912, 2020). "However, overexpression of TFDP1 did not correlate with altered expression levels either of its protein partner, E2F1, or one of the E2F1/TFDP1 regulators, RB, in our tumor cohort (data not shown)." (PMID 19995430, 2009).
infection (2 papers, 2016 to 2024). The state of being infected such as from the introduction of a foreign agent such as serum, vaccine, antigenic substance or organism. "In contrast, three days post infection, the mCherry+ cells containing sgRNAs against Tfdp1 and E2f4 showed a significant reduction in proliferation compared to control cells." (PMID 39043964, 2024). "To gain insights into the transcriptional regulation of Tfdp1 in HSPCs, we performed RNA-seq in sorted Tfdp1-KO HSPCs and Rosa26-targeted control HSPCs three days post infection." (PMID 39043964, 2024). "The labeled cells were then infected with sgRNA-expressing lentiviruses targeting Tfdp1, E2f4, or Rosa26, and analyzed one and three days post infection." (PMID 39043964, 2024).
TFDP1 also shares sentences with these, for which no sentence is quoted: leukemia (3 papers); systemic lupus erythematosus (2); adenocarcinoma (1); anemia (1); Anxiety (1); developmental verbal dyspraxia (1); esophageal squamous cell carcinoma (1); glioma (1); Intellectual disability (1); neuroblastoma (1); non-Hodgkin lymphoma (1); Pheochromocytoma and Paraganglioma (1); respiratory disorders (1); sarcopenia (1); schizophrenia (1); Sepsis (1).